CCL2 (C-C motif chemokine ligand 2)
Diseases named in the same sentence as CCL2 in open-access papers (continued):
Sharing a sentence is not in itself a finding about the gene and the disease.
lung carcinoma (continued). "Statins inhibit chemokine (C-C motif) ligand 3 (CCL3) secretion by primary lung cancer cells and suppress IL-6 and CCL2 production by mesenchymal stromal cells (MSCs), and disrupt the communication between lung cancer cells and MSCs." (PMID 38362156, 2024). "In lung cancer models, the chemokine monocyte chemoattractant protein-1 (CCL2) positively correlates with MDSC frequency, and antibody-mediated blockade of CCL2 reduces both G-MDSCs and M-MDSCs in tumours reducing iNOS and Arg1 expression." (PMID 38464388, 2024). "Herein, we aimed to shed light on the roles of PRPS2 in regulating the recruitment of TAM and MDSC, while also investigating the potential interplay between PRPS2 and CCL2 in the context of lung cancer." (PMID 38952044, 2024). "Application of the miR‐210‐3p mimic markedly impaired CCL2 mRNA and its protein levels, whereas the miR‐210‐3p inhibitor treatment significantly increased CCL2 expressions in A549 lung cancer cells." (PMID 35658112, 2024). "The impact of CCL2 on the recruitment of macrophages in tumorigenesis for lung cancer has also been highlighted." (PMID 39014491, 2024). "For lung cancer, bioinformatic analysis of the transcriptome of SCs demonstrated the secretion of high levels of CCL2, CXCL5, CXCL12, and CXCL8, and functional data suggested that CCL2 promoted the M2 polarization of macrophages." (PMID 38638689, 2024). "We found that CCL2 was highly expressed in the high metastatic lung cancer tissues but was less expressed in low metastatic lung cancer tissues." (PMID 37850256, 2024). "Lung cancer patients with bone metastases have increased serum CCL2, and shRNA KD of CCL2 in non-small cell lung cancer cells reduced intratibial tumor growth and bone resorption in SCID mice." (PMID 37025604, 2023). "This inhibition reduces CCL2 secretion in lung cancer cells and decreases the infiltration of monocytes/TAMs." (PMID 37656220, 2023). "This indicates that the CCL2 expressed in cancer cells potentially decreases the level of core fucose of the N-glycan in IgG in sera of patients with lung cancer." (PMID 37865317, 2023). "In lung cancer, it can significantly inhibit the proliferation of KRAS mutant lung cancer, downregulate the expression of programmed death-ligand 1 induced by interferon-gamma, and reduce the migration of Lewis lung cancer cells in a CCL2-dependent manner." (PMID 37716981, 2023). "Autophagy induced by TLR4 or TLR3 activation augments the production of various cytokines such as IL6, CCL2/MCP-1, CCL20/MIP-3α, and VEGFA by promoting TNF receptor-associated factor 6 ubiquitination, which ultimately drives lung cancer progression." (PMID 37484013, 2023). "At the baseline, the lung cancer cell lines were releasing detectable levels of CCL2, a potent chemokine for CD14+ cells." (PMID 36139660, 2022). "In this study, we explored the novel role of MRE11 in the IL6/STAT3/CCL2 signaling pathway in lung cancer." (PMID 36547079, 2022). "During tumourigenesis, tumourigenic signals such as Cxcl1 and Ccl2 induce Pdia4 overexpression and Stat3 phosphorylation and, subsequently, lead to an up‐modulation of Vegf proteins in lung cancer stromata." (PMID 35170261, 2022). "In lung cancer, the CCL2 signaling pathway is the key mechanism through which macrophages activate the growth and metastasis of lung cancer cells by triggering the bidirectional cross-talk between macrophages and these cells." (PMID 36547079, 2022). "Tumor-induced production of CXCL5 by SCs supported lung cancer spreading, epithelial-mesenchymal transition (EMT), and formation of metastasis in vivo, while SC-derived CCL2 promoted the M2 polarization of macrophages and lung cancer cell proliferation." (PMID 36551618, 2022). "The CCL2 signaling pathway is pivotal for the bidirectional cross-talk between macrophages and lung cancer cells during the growth and metastasis of cancer cells." (PMID 36547079, 2022).
lung carcinoma (continued). "Studies have reported that several chemokines, such as CCL2, CCL5, CCL4, CXCL19, and CXCL12, are associated with the progression, metastasis, and prognosis of lung cancer." (PMID 36118890, 2022). "CCL2 signaling is the important pathway through which macrophages can activate the growth and metastasis of lung cancer cells by triggering bidirectional cross-talk between macrophages and cancer cells." (PMID 36547079, 2022). "TXA2 and 12-HHT are direct chemoattractants for monocytes and TP stimulation of lung cancer promotes monocyte recruitment through the upregulation of MCP-1 and CCL2 expression, suggesting a role for TXA2 signaling in intra-tumoral recruitment of TAMs." (PMID 36234768, 2022). "The manifestation of an assemblage of IL-6 and IL-10 or CCR-2, CCL-2 connects to a shoddy projection in patients with lung cancer." (PMID 34336101, 2021). "DT was shown to inhibit the macrophage recruitment of lung cancer cells by decreasing the expression of chemokine (C-C motif) ligand 2 (CCL2) secreted from both lung cancer cells and macrophages." (PMID 34639167, 2021). "Statins inhibit the survival of lung cancer cells by inhibiting the secretion of CCL3 by lung cancer cells as well as IL-6 and CCL2 secretion by mesenchymal stromal cells, indicating the potential of statins as repurposed drugs for targeting the immune TME." (PMID 34303383, 2021). "At different stages of lung cancer, IL-6's mechanisms upregulated CCL-2/5 and played a part in the EMT and therapy resistance, a recent study in in vivo mouse and in vitro human lung tumour representations indicated." (PMID 34336101, 2021). "Suppression of neddylation in mouse Lewis lung cancer cells resulted in decreased CCL2 secretion and reduced infiltration of TAM into cancer tissues." (PMID 34445235, 2021). "Lung cancer cells mobilize TAMs to the cancer tissue by secreting CCL2, but the upstream of CCL2 is also actively investigated." (PMID 34445235, 2021). "Lung cancer cells can induce macrophage infiltration by increasing the production of CCL2 and CXCL3." (PMID 34616731, 2021). "Our study proved that ERα in lung cancer cells can promote the signal cross‐talk between lung cancer cells and macrophages via the ERα/CCL2/MMP9 and CXCL12/CXCR4 pathways." (PMID 32356397, 2020). "It has been previously reported that TLR4-induced autophagy activation promoted migration and invasion of lung cancer by induction of chemokines and immunosuppressive factors including CCL2, CCL20, IL-6, VEGFA, and MMP2." (PMID 32384667, 2020). "We have preliminary evidence that two different bathes of A009, sharing HyT as the most abundant polyphenols, reduce the production of VEGF and CXCL8 in A549 and H1650 lung cancer cells, and the production of CCL2 in A549 lung cancer cells." (PMID 32224910, 2020). "Western blotting results from tissue specimens in 719 patients with lung cancer revealed that patients with high CCL2 expression had significantly worse overall survival and progression-free survival." (PMID 33297571, 2020). "Our results show that CCL2 is directly regulated by ERα, and the increased CCL2 in lung cancer cells can further influence the M2 polarization and MMP9 production of macrophages." (PMID 32356397, 2020). "CCL2 also contributes to the acquisition of resistance to docetaxel in lung cancer and resistance to cisplatin in gastric cancer." (PMID 33297571, 2020). "IL10 also drives in vivo lung cancer growth and metastasis by upregulating the CCL2/C-C motif chemokine receptor 2 (CCR2) and C-X-C motif chemokine ligand (CXC3CL1)/C-X3-C motif chemokine receptor 1 (CX3CR1) axis in macrophage-tumor cell crosstalk." (PMID 32219066, 2020). "Experimental lung tumor models, in vitro TAMs-tumor cells, co-culture models, and human lung cancer biopsies demonstrated that CCL2/CCR2 signaling is one of the central signaling pathways involved in lung cancer growth and metastasis." (PMID 32219066, 2020).
lung carcinoma (continued). "On the one hand, higher expression of ERα in lung cancer cells can lead to more production of CCL2, which can then bind to CCR2 receptor on the membrane of the infiltrated macrophages." (PMID 32356397, 2020). "There is only one report illustrating that the blockade of CCL2 enhanced the immunotherapeutic effect of anti-PD1 in lung cancer." (PMID 30853982, 2019). "Inhibition of CCL2 with specific antibodies reduced tumor growth in different experimental models such as prostrate, melanoma, breast, liver, and lung cancer." (PMID 30853982, 2019). "Like our results, some authors indicated that the disruption of CCL2/CCR2 chemokine signaling has the ability to suppress A549 lung cancer cell proliferation and invasion." (PMID 31350989, 2019). "Marked changes in gene expression were measured for Ccl2, Ccl7, Ccl17, Ccl22, Ccl3, Ccl4, Il-1α, Il-1ß, and Il-1rn (inflammation), Lpo and Noxo1 (oxidative stress), and Mmp12 (inflammation/lung cancer)." (PMID 29463257, 2018). "For example, in subcutaneous tumors developed by LLC lung cancer cells, deletion of the Ccl2 gene in LLC cells reduces the number of macrophages in the tumors." (PMID 30483271, 2018). "Our results suggested that CCL2 is one of the critical cytokines that control the migration ability of DT-treated lung cancer cells." (PMID 29207614, 2017). "A previous study showed that bidirectional cross talk between TAM and lung cancer cells through CCL2/CCR2 signaling is a major mechanism of the TAM-mediated promotion of lung cancer growth and metastasis." (PMID 29207614, 2017). "We also clarified the inhibitory effect of 10 μM DT on the interaction between macrophages and lung cancer cells through blocking the CCL2 pathway." (PMID 29207614, 2017). "Altogether, our data suggested that DT inhibits the migration of both macrophages and lung cancer cells by blocking the expression of several cytokines, and CCL2 is one of these critical cytokines under DT treatment." (PMID 29207614, 2017). "Our data suggest that CCL2 is the one of the critical cytokines controlling the migration ability of DT-treated lung cancer cells." (PMID 29207614, 2017). "An in vitro ELISA analysis demonstrated that DT treatment inhibited CCL2 secretion from a lung cancer cell and macrophage coculture." (PMID 29207614, 2017). "A previous study demonstrated increased CCL2 levels in lung cancer patients with bone metastases compared with patients with localized tumors." (PMID 29207614, 2017). "Recently, we reported that CCR2 transduced tumor antigen-specific CD8+ T cell trafficking by CCL2 expression in lung cancer cells, which potentiated its in vivo anti-lung cancer reactivity." (PMID 28424406, 2017). "Our study suggested rs3760396 polymorphism of CCL2 is associated not only with prognosis of NSCLC, but also with risk of lung cancer in a subtype-specific manner." (PMID 27145753, 2016). "High serum CCL2 levels are part of the disease-induced systemic alterations that are correlated with a poor prognosis in breast, pancreatic and lung cancers." (PMID 26684239, 2016). "Our results pointed to a lung cancer subtype specific molecular mechanism link between CCL2 and adenosquamous carcinoma." (PMID 27145753, 2016). "Our results further supported previous evidence of the important role of CCL2 in lung cancer development." (PMID 27145753, 2016). "In this study, we found that CC chemokine 2 (CCL2) was produced to variable degrees by human lung cancer cell lines, and that LK79, a HLA-A*2402+ small-cell lung cancer (SCLC) cell line overexpressing WT1 mRNA, produced extremely high amounts of CCL2." (PMID 23441216, 2013). "Collectively, these results indicate that LCN2 facilitates cross-talk between tumor cells and astrocytes in the brain, activating astrocytes to secrete CCL2, thereby promoting macrophage recruitment and contributing to a protumorigenic microenvironment in the BM of lung cancer patients." (PMID 41436606, 2025).
lung carcinoma (continued). "For instance, CCL2 mediates the migratory response of breast and lung cancer cells." (PMID 39595551, 2024). "We found that TREM2 was strongly associated with CCL2, CCL3, CCL13, and CCL17 in lung cancer." (PMID 39135069, 2024). "However, the neddylation pathway in lung cancer can stimulate the NF-κB axis to promote the secretion of CCL2 for increasing infiltration and accumulation of TAMs to suppress lung cancer progression and mediate poor prognosis." (PMID 39014491, 2024). "Therapeutic CCL2-blockade also decreased the recruitment of MDSCs in both the blood and tumors collected from lung cancer-bearing mice and resulted in increased CD4+ and CD8+ T cell infiltration of tumors, higher production of IFNγ, and improved survival of tumor-bearing mice." (PMID 39114657, 2024). "Lung cancer CAFs exert their immunosuppressive effects by secreting chemokines, including CCL2, chemokine (C-C motif) ligand 7 (CCL7), chemokine (C-X-C motif) ligand 1, 5, and 8 (CXCL1, CXCL5, CXCL8), and IL-6, which promote the differentiation of CD14+ monocytes into immunosuppressive MDSCs." (PMID 39834587, 2024). "The secretion of CCL2 was regulated by CTNNAL1 in lung cancer cells." (PMID 37239133, 2023). "Also, CCR2 inhibitor can suppress CCL2-mediated lung cancer cell invasion by downregulating MMP-9 expression." (PMID 37325423, 2023). "CCL2 was shown to protect tumor cells and may even induce resistance, as shown for doce-taxel in lung cancer cells and for sorafenib in HCC." (PMID 37013652, 2023). "Furthermore, the upregulation of CCL2 is due to the increase of the stemness-related transcription factor TWIST, and the increased CCL2 secretion promotes the infiltration of M2 macrophages in lung cancer." (PMID 35740975, 2022). "The chemoresistance that occurs within lung cancer cells may be mediated by the stress response of CCL2‐expressing cells, implicating CCL2 as a possible target for augmenting the therapeutic efficacy of DTX on lung cancer." (PMID 35702353, 2022). "Moreover, CCL2 secretion was lower in MRE11-knockdown lung cancer cells than in control cells after treatment with the conditional medium of RAW264.7 cells." (PMID 36547079, 2022). "Lung cancer patients with high CCL2 expression have a poor prognosis." (PMID 36547079, 2022). "Furthermore, the result showed that the expression level of GPX8 was positively correlated with IL6 and CCL2 in lung cancer." (PMID 35978854, 2022). "CCR2 is the receptor for CCL2 which induces monocyte infiltration in tumors including lung cancer; therefore, MAFB may be a potential indicator for monocyte infiltration." (PMID 36077342, 2022). "Knockdown of GPX8 obviously inhibited LUAD metastasis through the modulation of focal adhesion pathway and GPX8‐mediated IL6 and CCL2 production of CAF may play crucial role for lung cancer metastasis." (PMID 35978854, 2022). "The results suggest that MRE11 could regulate the microenvironment of lung cancer through the CCL2 pathway." (PMID 36547079, 2022). "Epigenetic mechanisms could be involved in CCL2 repression in neuroblastoma, as recently described in lung cancer, where epigenetic silencing of CCL2 by DNMT1 and the EZH2/H3K27me3 axis potentiates tumor development by inhibiting macrophage infiltration." (PMID 36923280, 2022). "CCL2 promotes lung cancer cells' growth, migration and invasion." (PMID 34464477, 2021). "Circulating levels of CCL2 also increase in lung cancer patients and correlate with poor survival." (PMID 32528880, 2020). "The results from western blots revealed that CM from coculture of THP‐1 cells or primary B6 Mφ cells with lung cancer cells could increase the expression of ERα, and CCL2, in lung cancer A549, H1299, and LLC1 cells." (PMID 32356397, 2020). "Together, the interactions between lung cancer cells and macrophages through ERα/CCL2/CCR2/MMP9 and CXCL12/CXCR4 pathways could promote the NSCLC progression." (PMID 32356397, 2020).
lung carcinoma (continued). "Furthermore, preclinical studies from NSCLC animal models show that lung cancer cells can induce the macrophage infiltration through increasing CCL2 and CXCL3 production of NSCLC cells." (PMID 32356397, 2020). "In this case, CCL2 expression in cancer cells is promoted by activation of the mammalian target of rapamycin complex 1 (mTROC1) pathway that is frequently activated in various types of cancer including lung cancer." (PMID 30483271, 2018). "In addition, 10 μM DT suppressed the macrophage recruitment ability of lung cancer cells by reducing CCL2 secretion from both macrophages and lung cancer cells." (PMID 29207614, 2017). "However, there are some concerns about this since in mouse lung cancer models, stopping anti-CCL2 therapy results in a rapid regrowth of tumor with enhanced metastasis." (PMID 28143493, 2017). "In lung cancer, CCL2 signaling pathway is the important mechanism that TAMs can activate the growth and metastasis of lung cancer cells through the bidirectional cross talk between macrophages and lung cancer cells." (PMID 29207614, 2017). "According to the findings of the previous report and the present study, DT may inhibit the migration of both macrophages and lung cancer cells by blocking the expression of several cytokines, and CCL2 may be one of these critical cytokines under DT treatment." (PMID 29207614, 2017). "The minor allele of SNP rs3760396 of CCL2 gene is associated with increased risk of adenosquamous lung carcinoma, but not overall lung cancer in Chinese Han ethnicity population." (PMID 27145753, 2016). "Having evaluated CCL2 depletion in colon and lung carcinoma cell lines and determined that CCL2 expression levels were regulated both intracellularly and extracellularly, we wanted to examine in more detail how CatS was regulating CCL2." (PMID 26358505, 2015). "Introduction of the CCL2/CCR2 axis successfully potentiated in vivo anti-lung cancer reactivity mediated by CD8+ T cells double gene-modified to express WT1-specific TCR and CCR2 not only via CCL2-tropic tumor trafficking, but also CCL2-enhanced WT1-responsiveness." (PMID 23441216, 2013). "Based on these results, we may surmise that CCL11 and IP-10 are specifically increased in plasma from pulmonary tuberculosis and tuberculous pleurisy patients, while CCL8 and CCL2 are specifically decreased when compared with lung cancer controls." (PMID 23028695, 2012). "Moreover, the protein level of CCL2 was elevated in lung cancer." (PMID 39135069, 2024). "By using the expression pattern of signature genes identifying the N1 state (Tnf, Fas), the N2 state (Arg1, Ccl2), and immature neutrophils (Stmn1, Ube2c), pseudotime analysis confirmed the developmental direction of TANs with N2 as an early state of TANs in the lung cancer TME." (PMID 37002229, 2023). "Therefore, blocking the STAT3/CCL2 signaling pathway may aid in the cessation of lung cancer progression." (PMID 36547079, 2022). "Similarly, CCL2 also contributes to the chemoresistance of lung cancer cells to docetaxel, which may be attributed to cell stress responses." (PMID 34464477, 2021). "Notably, the CCL2 signaling pathway is a prominent mechanism through which TAMs promote the growth and metastasis of lung cancer cells through bidirectional interactions between lung cancer cells and macrophages." (PMID 34639167, 2021). "Moreover, increasing numbers of THP‐1 cells within the coculture system could also lead to increase the expression of ERα and CCL2 in the lung cancer cells in a dose‐dependent manner." (PMID 32356397, 2020). "Additionally, activation of TLR4 and TLR3 stimulated autophagy induction in lung cancer cells and induced enhancements of cytokine productions, such as IL-6, CCL2/MCP-1, CCL20/MIP-3α, VEGFA, and MMP2, by encouraging TRAF6 ubiquitination, thereby led to increases of cell migration and invasion." (PMID 31620128, 2019).